EGFR (epidermal growth factor receptor)
Diseases named in the same sentence as EGFR in open-access papers (continued):
Sharing a sentence is not in itself a finding about the gene and the disease.
glioblastoma (continued). "Moreover, EGFR enhancer-perturbation increases the sensitivity of GB cells to TMZ, the first-choice chemotherapeutic agent to treat glioblastoma." (PMID 37803333, 2023). "Gefitinib, in a phase II trial, showed uptake and efficacy in dephosphorylating EGFR in human glioblastoma samples, but no change in downstream EGFR pathway activity." (PMID 36765632, 2023). "Our results show that in the setting of newly diagnosed glioblastoma, EGFR-amplified compared to EGFR non-amplified tumours display altered gene expression in the EGFR pathway, but this distinction is lost in the setting of recurrent disease." (PMID 36765632, 2023). "Finally, BDTX-1535 is another inhibitor that is currently being explored in a first-in human clinical trial for patients with glioblastoma and NSCLC harboring sensitive EGFR alterations and who have disease progression following standard of care (NCT05256290)." (PMID 36765799, 2023). "We found 9849 significantly differentially methylated CpGs (DMCGs) with Δβ ≥ 0.1 and p-value < 0.05 in EGFR amplified, compared to EGFR non-amplified glioblastomas." (PMID 37444635, 2023). "Despite the limited success of targeting glutamatergic receptors and the association of these receptors with EGFR-dependent pathways involved in cell survival, targeting EGFR has not proven successful in glioblastoma treatment for several reasons." (PMID 36614191, 2023). "In summary, dissecting the methylomes of EGFR amplified and non-amplified glioblastomas revealed altered DNA replication, DNA packaging, chromatin silencing and gene silencing pathways, opening potential novel targets for future precision medicine." (PMID 37444635, 2023). "For this study, we subsequently selected 50 glioblastomas with known EGFR amplification status: 25 with amplified EGFR gene region, and 25 without amplified gene region." (PMID 37444635, 2023). "Two studies used IF in combination with FISH to determine whether cells that lined blood vessels and expressed endothelial markers also demonstrated amplification of epidermal growth factor receptor (EGFR), a common genetic alteration in glioblastoma." (PMID 36823554, 2023). "Furthermore, CD3/Fn14 BiTE, CD3/B7-H3 BiTE, CD3/EGFR BiTE, and CD3/IL13Rα2 BiTE have also shown promising results in preclinical studies of glioblastoma and hepatocellular carcinoma (HCC)." (PMID 37596653, 2023). "EGFRvIII is overexpressed in 50%–60% of EGFR-amplified glioblastomas and constitutes a negative prognostic factor." (PMID 37908227, 2023). "Since EGFR is an interesting candidate in precision medicine, we performed an integrated molecular analysis in glioblastoma with and without EGFR amplification." (PMID 37444635, 2023). "Dacomitinib is a second-generation EGFR inhibitor that has been tested in a phase II clinical trial of recurrent glioblastoma patients with EGFR-amplified tumours either with or without EGFRvIII expression." (PMID 37857607, 2023). "The EGFR copy number alterations can be used clinically for the diagnosis and classification of GBM’s, helping to distinguish them from other tumors with similar histological features, these amplifications being almost specific exclusively to glioblastomas." (PMID 37446288, 2023). "We report no significant cross‐reactivity of GCT02 to EGFR protein, demonstrating a highly specific new binder for glioblastoma." (PMID 36890859, 2023). "The increase in cancer cell migration may be inhibited by combined treatment with VEGFR2 and epidermal growth factor receptor (EGFR) antibodies, as demonstrated by a decreased in vitro migration of glioblastoma cells." (PMID 38148844, 2023). "Since EGFR amplification is a promising novel candidate in precision medicine, we performed an epigenome-wide DNA-methylation analysis of EGFR amplified and non-amplified glioblastomas." (PMID 37444635, 2023).
glioblastoma (continued). "On the other hand, a recent study showed that overexpression of miR-424 strongly suppressed cell proliferation and migration rate in glioblastoma cells, by targeting genes such as KRAS, RAF1, and MAP2K1, from the epidermal growth factor receptor (ERBB) signaling pathway." (PMID 37047673, 2023). "On the other hand, various investigators have also reported increased sensitization of tumor cells to radiotherapy through EGFR inhibition in head and neck squamous cell carcinoma (SCC), human colon cancer (GEO), colon cancer, ovarian (OVCAR-3), glioblastoma multiple." (PMID 38026933, 2023). "Our findings, taken together, reinforce that glioblastoma is incredibly heterogeneous, and that there are crucial biological differences between EGFR-amplified and non-amplified tumours." (PMID 36765632, 2023). "EGFRvIII was detected in 16/112 (14%) glioblastomas, 13/49 (27%) EGFR amplified glioblastomas, and 3/63 (5%) EGFR non-amplified glioblastomas." (PMID 38201434, 2023). "Recurrent glioblastoma tumors with an alteration in MAPK pathway could belong to the mesenchymal subtype and respond poorly to regorafenib treatment, while EGFR-altered cases have a better response to regorafenib." (PMID 36171338, 2022). "EGFRvIII is a glioblastoma-specific tumor antigen and EGFR is highly expressed in glioblastoma and normal tissues, such as skin, but not in normal brains." (PMID 36059449, 2022). "Only 2/6 of the NF1-associated glioblastomas from our study had the combination of trisomy 7 and monosomy 10, and none harbored TERT promoter mutation or EGFR amplification." (PMID 35945463, 2022). "However, the third-generation EGFR inhibitor osimertinib (AZD9291), which crosses the BBB and inhibits the proliferation of glioblastoma cells, is very promising." (PMID 35214064, 2022). "While the aberrant EGFR expression in that study was not a downregulation of wild-type EGFR, rather expression of a common glioblastoma mutation (EGFRvIII), it supports the idea that specific cohorts of GBM patients may benefit from combined EGFR-targeting and TMZ therapy." (PMID 36316307, 2022). "In our recent study evaluating the efficacy of osimertinib against EGFRvIII+ glioblastoma, we found that compared to D317, D10-0171 exhibited increased expression of growth-promoting GSC markers such as OLIG2, and resistance to growth inhibition by EGFR-TKIs." (PMID 35456993, 2022). "In the case of MYBL2, this may be due to EGFR signaling, which is frequently amplified and overexpressed in IDH-wildtype glioblastomas and was reported to activate the MYBL2 promoter in association with E2F1." (PMID 35228525, 2022). "The EGFR protein is minimally expressed or even absent in healthy cerebral tissue, but is overexpressed in 40–60% of glioblastoma tumors." (PMID 35203609, 2022). "To elucidate 3D genome structure alteration and its possible consequences in EGFR-amplified glioblastoma, in this study, we performed a comparative analysis of Hi-C, RNA-seq, and whole-genome sequencing (WGS) on EGFR-amplified glioblastoma-derived A172 and normal astrocytes (HA1800 cell line)." (PMID 35521558, 2022). "In addition, afatinib inhibits EGFR-mediated PI3K/AKT/mTOR signaling in vitro and in vivo in neuroblastoma cells and inhibits tumorigenesis in glioblastoma by inhibiting EGFR/AKT signaling." (PMID 36297833, 2022). "It has been recently reported that the TLK1 paralog, TLK2, could form a complex with Src and activate the EGFR/Src/FAK signaling pathway to promote the migration and invasion of breast adenocarcinoma and glioblastoma cells." (PMID 36497211, 2022). "For glioblastoma, CAR-NK efforts are mainly focused on targeting EGFRvIII, EGFR, and HER2." (PMID 35203609, 2022).
glioblastoma (continued). "There is also evidence that the absence of EGFR amplification, TERT promoter mutation, and + 7/− 10 is associated with a better clinical course in tumors that qualify as IDH-wildtype glioblastoma by histologic features alone." (PMID 35978439, 2022). "The aim of this study was to discover new cyclic peptide ligands that selectively bind to both EGFR and EGFRvIII and evaluate the targeting cytotoxicity of their PDCs bearing the topoisomerase I inhibitor camptothecin (CPT) for NSCLC and glioblastoma cell lines." (PMID 35890400, 2022). "Pathology includes glioblastoma (3/3), methylguanine-DNA methyltransferase (MGMT) methylated (2/3), isocitrate dehydrogenase 1 (IDH1) mutant (0/3), epidermal growth factor receptor (EGFR) amplification (0/3), and α thalassemia/mental retardation syndrome X‐linked (ATRX) (3/3)." (PMID 36148206, 2022). "The EGFR gene, which showed a significant downregulation in Non-Resp samples, is consistent with literature data showing that glioblastoma TMZ-resistant cell lines lack EGFR activation and expression." (PMID 36132155, 2022). "Based on our present study, we describe for the first time how iPA promotes necroptosis in glioblastoma cell lines: U87MG, the same ones engineered to overexpress EGFR wild-type (wt) or EGFRvIII, and in GBM cells derived from a tumor biopsy of patients affected." (PMID 35393392, 2022). "Since the EGFR signaling pathway has been reported to induce CCL2 expression to recruit macrophages in glioblastoma, we propose that ADAM8 could induce TAM recruitment by regulating CCL2 expression via HB-EGF/EGFR." (PMID 36230833, 2022). "This upregulation by EGFR signaling is GBP-1-dependent and contributes to glioblastoma invasion." (PMID 35681772, 2022). "Notably, Src is a major component of the processes and pathways that regulate glioblastoma (GBM) tumorigenesis, such as proliferation, invasion, migration, and the epidermal growth factor receptor, Ras/Raf/MEK, and PI3K/AKT pathways." (PMID 35927718, 2022). "Moreover, GBP1 is induced by EGFR signaling and promotes invasion because it is required for the EGF-induction of MMP1 in glioblastoma." (PMID 34439200, 2021). "The glioblastoma cell lines without EGFR amplification were less sensitive to cinobufagin compared with the EGFR-overexpressed GBM cells." (PMID 34925034, 2021). "In glioblastoma, this pathway downstream of EGFR is often hyperactivated not only by overexpression or activating EGFR mutations but also by Phosphatase and tensin homolog (PTEN) deletion or downregulation, which antagonizes PI3K activity." (PMID 34681618, 2021). "SIACI of cetuximab, an anti-epidermal growth factor receptor (EGFR) mAb, has been safe and well tolerated in patients with recurrent glioblastoma in a phase I/II trial, with no dose-limiting toxicity (DLT) up to 250 mg/m2; a phase II trial is ongoing." (PMID 34063335, 2021). "Striking data in line with these assumptions come from the virtual absence of EGFR amplification in glioblastoma cell models in vitro, whereas it is found in about half of the diagnosed glioblastoma tumors." (PMID 33955157, 2021). "Differently, in RAS/RAF WT models resistant to EGFR inhibition, pevonedistat had no major effects on the EGFR pathway, as previously reported for glioblastoma and human myeloma." (PMID 34359705, 2021).
glioblastoma (continued). "Amongst the genes down-regulated by miR-34a, we selected five genes (ATM, EGFR, BCL2, MET, UGCG) for validation as they have been shown pre-clinically to play critical roles in cell survival and therapeutic resistance in the context of glioblastoma." (PMID 33765907, 2021). "Additionally, in glioblastoma multiforme (GBM), epidermal growth factor receptor (EGFR) and rictor-mediated pathways have been shown to play a key role in chemoresistance (increased viability)." (PMID 34572083, 2021). "Melanoma and glioblastoma cell lines express HB-EGF and TGF-α, the main ligands of EGFR." (PMID 34360915, 2021). "Mechanistically, EGFR signaling together with an interaction between Lpd and the Rapamycin-insensitive companion of mammalian target of rapamycin (RICTOR) jointly regulate glioblastoma radiosensitivity." (PMID 34771501, 2021). "EGFR is overexpressed in a majority of primary glioblastomas but not in the normal brain parenchyma, making it an attractive target for a number of fluorescent antibody-based probes." (PMID 34298721, 2021). "The protein expression level of LANCL2, rather than EGFR, was elevated in relapsing glioblastoma, compared with newly diagnosed glioblastoma." (PMID 34461927, 2021). "In Murat’s dataset, the expression of EGFR was 10.667 times higher in glioblastoma tissues than in normal tissues." (PMID 33892666, 2021). "Epidermal growth factor receptor (EGFR) overexpression, PTEN (MMAC I) mutation, CDKN2A (p16) deletion, and less frequently MDM2 amplification are just a few defects which lead to uncontrolled proliferation, invasion, and angiogenesis in primary glioblastoma (GBM)." (PMID 32178454, 2020). "Thus, both p-EGFR and ZNF263 can be used as an indicator for poor prognosis while SIX3 serves as an indicator for favorable prognosis of glioblastoma." (PMID 32051553, 2020). "EGFR DNA, RNA and protein contained in tumour-derived EVs are now being investigated as potential biomarkers for cancers including breast, glioblastoma, lung, ovarian and prostate." (PMID 33143170, 2020). "As described recently, “adult-type” grade II diffuse astrocytomas with no IDH mutations often harbor EGFR amplification, TERT promoter mutations or combined whole chromosome 7 gain and whole chromosome 10 loss and have glioblastoma-like behavior." (PMID 32771057, 2020). "EGFR1 and EGFR3 assays strictly correlated with FISH results, making it possible to distinguish all EGFR-amplified (8/8) and EGFR-non-amplified glioblastoma (11/11), with sensitivity, specificity, positive and negative predictive values of 100%." (PMID 32303258, 2020). "After generating a number of treatment resistant Glioblastoma cell lines we observed that resistant cell lines lacked EGFR activation and expression." (PMID 33082482, 2020). "ERK and CK2α were recently found to promote DNA replication in an EGFR dependent manner in human glioblastoma cells by decreasing an ADP-dependent negative feed-back regulation acting on CDC7/ASK51." (PMID 32612138, 2020). "Furthermore, we show that glioblastoma cells that have survived long-term, undergo repeated TMZ and irradiation treatment or cells that intrinsically express low EGFR and are resistant to treatment all have high levels of miR-221." (PMID 33082482, 2020). "Caveolin-1 is also among the proteins enriched in sEVs derived from EGFRvIII overexpressing glioblastoma cells, highlighting its role as a mediator of non-canonical EGFR signalling and as a stress survival mechanism." (PMID 33302515, 2020). "Correlation analysis showed a negative correlation between expression of miR-7-5p and EGFR in 21 glioblastoma tissues." (PMID 32962742, 2020). "EGFR alterations in glioblastoma lie primarily in the extracellular domain, unlike the kinase domain alterations seen in NSCLC." (PMID 33187135, 2020).
glioblastoma (continued). "EGFRvIII, an oncogenic EGFR mutant without exons 2–7 that is universally observed in glioblastoma multiforme, is constitutively active and poorly ubiquitinated, conferring inefficient receptor trafficking to lysosomes and prolonged oncogenic signaling." (PMID 32943616, 2020). "In addition, numerous studies have suggested that EGFR is overexpressed in most primary GBM and is characteristic of more aggressive glioblastoma phenotypes." (PMID 32045997, 2020). "The EGFR3 assay allowed for the identification of EGFR copy gain in 16 EGFR-non-amplified glioblastomas with a mean copy number of 3.3 (range 2.6–3.9)." (PMID 32303258, 2020). "The mechanistic and therapeutic insights in the kinase domain have not yet translated into clear therapeutic efficacy in glioblastoma, where it is still unclear how the specific EGFR ectodomain alterations—EGFRvIII in particular—can be properly targeted." (PMID 33187135, 2020). "For example, in glioblastoma multiforme 18, no significant change was observed in cell proliferation in IL13RA2 loss tumor cells with the absence of mutant EGFR (EGFRvIII)." (PMID 31823484, 2020). "Despite increased interest in the role miRNA regulation plays in glioblastoma tumorigenesis, specific miRNA regulation of EGFR in has not been studied extensively." (PMID 33082482, 2020). "EGFR hyperactivation has been found to transcriptionally suppress the expression of DNA demethylase-TET oncogene family member 1 (TET1), which contributes to the hypermethylation in the promoter region of a panel of TSGs in lung cancers and glioblastomas." (PMID 32051553, 2020). "Epidermal growth factor receptor (EGFR) has long represented an oncologic target of immense interest, and it is overexpressed in several malignancies, including head and neck cancer, ovarian cancer, and glioblastoma." (PMID 31898555, 2020). "We showed that miRNA-7 markedly inhibited the expression of EGFR and decreased the growth of glioblastoma cells, relative to blank control and negative control miRNA (p < 0.05)." (PMID 32592373, 2020). "While many other factors are likely at play (such as redundancy of regulatory circuits), it is clear that present-day inhibitors simply do not inhibit downstream signal transduction of EGFR in glioblastoma effectively." (PMID 33187135, 2020). "miR-494 enhances invasiveness of gliomas via EGFR upregulation, protein kinase B (Akt) activation, and extracellular signal-regulated kinase (ERK) activation, and downregulation of this miRNA in glioblastoma stem-like cells leads to increased apoptosis and suppresses invasion and proliferation." (PMID 32258065, 2020). "Therefore, we demonstrated that LPP-AS2 regulates EGFR expression and activates the PI3K/AKT/c-MYC signaling pathway by competitively sponging miR-7-5p, thereby promoting glioblastoma cell viability." (PMID 32962742, 2020). "However, the exact change to the expression levels of EGFR during and post-treatment with TMZ and irradiation in the glioblastoma setting is not well understood." (PMID 33082482, 2020). "In the group of patients with an IDH-wt glioblastoma, three had a rare histological subtype (1 with giant cell glioblastoma and 2 with gliosarcoma), and none of the three tumors had EGFR amplification." (PMID 32303258, 2020).